BRAF (B-Raf proto-oncogene, serine/threonine kinase)
Diseases named in the same sentence as BRAF in open-access papers (continued):
Sharing a sentence is not in itself a finding about the gene and the disease.
colorectal tumors (continued). "The proximal colon is a common site for BRAF-mutated, MSI, and CIMP colorectal tumors, which disproportionately impact women." (PMID 39031216, 2024). "Overall, our study demonstrates that SRC signaling is at the nexus of a cell-autonomous inflammatory program with pro-tumorigenic activities, which explains why BRAFV600E colorectal tumors develop resistance to BRAF/MEK and EGFR inhibitors." (PMID 36759733, 2023). "Previous research has found that the prevalence of HER2 overexpression is higher in RAS/BRAF wild-type colorectal tumors." (PMID 36672503, 2023). "Based on the combination of these molecular markers (MSI, CIMP, and BRAF and KRAS mutations), colorectal tumors can be classified according to three carcinogenic pathways." (PMID 37107652, 2023). "Previous study reported that B-Raf protooncogene, serine/threonine kinase (BRAF), and KRAS protooncogene, GTPase (KRAS) mutations, are early molecular alterations in serrated lesions and are mutually exclusive in colorectal neoplasms." (PMID 34545326, 2021). "Approximately 35–45% of patients with colorectal tumors have mutation in KRAS gene, while BRAF V600E mutation is found in about 5–15% of colorectal adenocarcinomas." (PMID 29127628, 2019). "In fact, current molecular phenotyping of colorectal tumors is usually linked to the traditional determination of somatic mutations in well-known oncogenes such as KRAS and BRAF." (PMID 30537927, 2018). "While the concordant BRAF mutation and the MSI status were observed in 100% (18 of 18) paired samples of primary colorectal tumours and corresponding ovarian metastases, the KRAS mutation concordance was observed in 83.3% (15 of 18) of them." (PMID 29662660, 2018). "The colorectal tumors expressing CD274(PD-L1) was reported that associated with poorly prognostic factors such as poorly differentiation, BRAF mutation and ‘stem-like’ immunophenotype features." (PMID 29108360, 2017). "It is shown that pre-treatment of SMAC-mimetics followed by their combined treatment with BRAF inhibitors can decrease cell viability, migration and can very efficiently sensitize colorectal tumour cells to apoptosis." (PMID 27520705, 2016). "CIMP was found to be strongly associated with BRAF mutation, MSI-H, and proximally located colorectal tumours." (PMID 24812557, 2014). "After flow-sorting, keratin-positive epithelial tumor fractions and vimentin-positive stromal fractions of 14 colorectal tumors were successfully analyzed, of which eight were BRAFp.V600E and six were BRAF wild type." (PMID 24244575, 2013). "MSI and loss of expression of MLH1 due to promoter hypermethylation are frequently associated with BRAF mutation and CIMP in MSI sporadic colorectal tumours." (PMID 18782444, 2008). "Future research should also further validate the diagnostic efficacy of FC across different ethnic populations, clarify its relationship with colorectal tumors staging and localization, and explore its association with tumor molecular characteristics (such as KRAS mutations, BRAF mutations)." (PMID 40703287, 2025). "In this work, we tested whether carfilzomib could restrain the growth of BRAF-mutant colorectal tumors not only by targeting cancer cells directly, but also by promoting an immune-mediated antitumor response." (PMID 38348572, 2024). "Synchronous colorectal tumors often show MSI, CIMP, and BRAF mutations." (PMID 38791280, 2024).
colorectal tumors (continued). "For example, activating mutations in the Kirsten Rat Sarcoma Viral Oncogene Homolog (KRAS) or V-Raf Murine Sarcoma Viral Oncogene Homolog B (BRAF) oncogenes confer proliferative characteristics and are found in 30% or 15% of sporadic colorectal tumours, respectively." (PMID 35326545, 2022). "The major aim of this study was to evaluate the performance of anti-BRAF V600E (VE1) antibody in colorectal tumors with and without KRAS mutation." (PMID 29127628, 2019). "Our result of the specific down-regulation of miR-193a-3p in BRAF-mutant colorectal tumors is in line with these previous reports, suggesting that miR-193a-3p may be involved in oncogenesis of various malignancies with mutated BRAF." (PMID 29115941, 2017). "However, activating mutations in BRAF and KRAS only occur in approximately 5-15% and 30-45% of colorectal tumours, respectively." (PMID 27248823, 2016). "In fact, in colorectal tumors, the elevated levels of Rac1b expression were significantly associated with mutant BRAF but not with mutant K-RAS genotype, suggesting that RAC1b is needed to sustain BRAF-induced but not RAS-induced cell transformation." (PMID 27127508, 2016). "Up to 60% of colorectal tumors exhibit gain-of-function mutations in KRAS, NRAS and BRAF genes." (PMID 27582544, 2016). "Accordingly, colorectal tumour BRAF V600E status, or colorectal/endometrial tumour MLH1 promoter methylation (that are rarely detected in Lynch Syndrome associated tumours), are very informative for identifying probable non-causal variants among mismatch-repair-deficient tumours." (PMID 25831438, 2015). "Only 3 and 2 depressed colorectal neoplasms had mutations in KRAS and BRAF respectively." (PMID 25551625, 2014). "KRAS mutations were encountered in 40% of appendiceal vs. 30% colorectal tumors, while BRAF mutations were seen in 40% of colorectal PM and none of the patients with appendiceal PM (p = 0.06)." (PMID 25593974, 2014). "In addition, increased EGFR expression in BRAF(V600E) colorectal tumors has been shown to correlate with vemurafenib resistance." (PMID 24023633, 2013). "However, among six BM from colorectal tumors, we identified KRAS mutations in three cases and BRAF mutations in two other cases." (PMID 23930206, 2013). "However, several reports showed that mutations in genes involved in the Ras-Raf-MAPK pathway, like KRAS and BRAF, are important biomarkers for colorectal tumor patient response to anti-EGFR mAbs." (PMID 23207070, 2012). "Colorectal tumours with RASSF2 methyaltion showed K-ras/BRAF mutations significantly more frequently than those without RASSF2 methyaltion, although earlier studies have showed that K-ras mutation and RASSF2 methylation are mutually exclusive." (PMID 16265349, 2005). "No BRAF mutations were detected in the colorectal tumors (IMN and CRC) examined in this study." (PMID 29796160, 2018). "Thus, new biomarkers must be identified to further characterize BRAF or KRAS mutation-negative colorectal tumours." (PMID 27248823, 2016). "Recent data from our group evaluating 24 patients with CRC shown that most colorectal tumors were microsatellite stable (98%), CIMP-low (92%), and had wild-type KRAS (69%) and BRAF (91%)." (PMID 35648382, 2023). "Our nationwide study clearly demonstrates that BRAF V600E and KRAS G12C colorectal tumours show significantly detrimental clinicopathological features." (PMID 37240418, 2023). "This study provides evidence that BRAF oncogene induces the expression of key autophagic markers, like LC3 and BECN1 in colorectal tumor cells." (PMID 26802026, 2016).
colorectal tumors (continued). "The findings of this study are expected to provide novel efficient protocols for treatment of otherwise resistant colorectal tumors bearing BRAFV600E, by exploiting the autophagic properties induced by BRAF oncogene." (PMID 26802026, 2016). "The molecular characteristics in this cohort demonstrate the general distribution within colorectal tumors and mutual exclusivity of the oncogenes KRAS and BRAF." (PMID 25742883, 2015). "This was derived from an individual carrying a quadruple wild-type (KRAS, NRAS, BRAF and PIK3CA) colorectal tumour, and thus recapitulates the molecular profile of patients sensitive to anti-EGFR antibodies." (PMID 26392303, 2015). "The same experimental strategy was then applied to an independent PDX that was also derived from a quadruple wild-type (KRAS, NRAS, BRAF and PIK3CA) colorectal tumour and was sensitive to EGFR blockade." (PMID 26392303, 2015). "A study on colorectal tumors found a positive correlation between TRAP1 and BRAF levels." (PMID 34831420, 2021). "The inclusion of hypermethylation analysis for MLH1 in colorectal tumors would also represent an opportunity to screen out sporadic cases, as not all can be found by BRAF testing." (PMID 32700475, 2020). "Furthermore, it is a remarkable fact that colorectal tumor is a disease due to different genetic and epigenetic alterations, such as microsatellite instability and activation of oncogenes including KRAS and BRAF." (PMID 30636375, 2019). "Therefore this study provides for the first time, a comparative study of BRAF, KRAS and HRAS oncogenes regarding their differential regulation of autophagic markers and related properties in colorectal tumor cells." (PMID 26802026, 2016). "This pathway involves the accumulation of inhibitory mutations at the level of tumor-suppressor genes and activating mutations at the level of oncogenes and are associated with colorectal tumors exhibiting MSS, non-CIMP, CIN, absent KRAS and BRAF mutations, and APC mutations." (PMID 29652830, 2018). "However, MLH1 promoter methylation has been shown to be superior to BRAF as a negative predictor in colorectal tumours, and the main indicator of non-pathogenicity in endometrial tumours where BRAF V600E status has no predictive value at all." (PMID 25831438, 2015). "However, an independent metachronous colorectal tumour or additional clinicopathological features not used in ascertainment (BRAF, MLH1 promoter methylation) could be assayed in the index tumour to aid in the interpretation of uncertain variants." (PMID 25831438, 2015). "However, JNMF found that co-module #30, enriched with the features of colorectal tumours, was only sensitive to MEK inhibitor and did not exert efficacy to BRAF inhibitor." (PMID 29950679, 2018).
thyroid tumor (117 papers, 2006 to 2026). A benign or malignant neoplasm affecting the thyroid gland. "Human thyroid tumors are often characterized by activating point mutations in BRAF, NRAS, HRAS, or KRAS, leading to the overactivation of MAPK- and mTOR-signaling pathways." (PMID 40711277, 2025). "The BRAF V600E mutation is prevalent in thyroid tumors, especially in PTC and HGFCTC but relatively infrequent in NSCLCs." (PMID 39980562, 2025). "A recent study from our group observed that the genetic and transcriptomic alterations seen in BRAF inhibitor resistance were also associated with thyroid tumor dedifferentiation." (PMID 38275291, 2024). "Rearrangements involving receptor tyrosine kinases, primarily RET, are present in a subset of thyroid tumors that lack mutations in either BRAF or RAS." (PMID 39596225, 2024). "Osteopontin expression has also been previously associated with BRAF mutations, particularly in thyroid tumors." (PMID 39410512, 2024). "Thyroid tumor dedifferentiation and BRAF inhibitor resistance are also found to be associated with a transition to an immunosuppressed state." (PMID 38275291, 2024). "We report for the first time three BRAF non-V600E variants previously undetected in thyroid tumors, including one concomitant with TERT mutation and associated with distant metastasis." (PMID 36835466, 2023). "Different studies of thyroid tumors have identified the activating mutation of BRAF as the main genetic alteration of this pathway, with the BRAF V600E hotspot mutation being the most frequently found genetic event." (PMID 37446330, 2023). "The gene expression and DNA methylation profiles of BRAF- and RAS-driven thyroid tumors are distinct, indicating that different sets of proteins are likely associated with BRAF- or RAS-driven tumors." (PMID 36056964, 2022). "BRAF is the most frequently mutated gene in thyroid tumors and has been the target of several clinical trials, including for advanced forms of the disease that are refractory to conventional therapy." (PMID 36056964, 2022). "BRAF V600E IHC can be used as an alternative to molecular biology to detect mutations in patients with thyroid neoplasm." (PMID 35646190, 2022). "Overall our data suggest that, in contrast to what has been reported in other tumor types, DEL-22379 is functional only in thyroid tumor cells harboring BRAF mutations." (PMID 36056964, 2022). "We aimed to assess the incidence of the BRAF V600E mutation in thyroid neoplasms at a tertiary care center and its association with various phenotypic features." (PMID 34345541, 2021). "According to the literature, in early thyroid follicular carcinoma, the methylation of the RASSF1A gene promoter is inversely related to the BRAF gene mutation during the occurrence of thyroid tumours." (PMID 34923978, 2021). "To date, BRAF gene mutations have been found confined to thyroid tumors with papillary differentiation." (PMID 34934597, 2021). "Some scholars hold the opinion that dual BRAF mutations and gene fusions can exist in the same thyroid tumor." (PMID 33520689, 2020). "Among the 11 thyroid tumor samples, BRAF (5/11, 45.5%) was the gene most frequently mutated, followed by NRAS (3/11, 27.3%)." (PMID 32333269, 2020). "Overall, we showed the concurrent expression of α-SMA, LOX, and COL1A1 genes and proteins in BRAF-driven human thyroid tumors, where we also detected stroma associated local invasion." (PMID 31906302, 2020). "In effect, BRAF mutation induces a reduction in I131 uptake in thyroid tumours, through several genetic and epigenetic mechanisms." (PMID 31093278, 2019). "Quantitative assessments of RARβ and its association with BRAF mutations have revealed promoter methylation of this gene in thyroid tumor genesis." (PMID 28926589, 2017). "Several studies further defined the relationship between the BRAF mutation and the aggressiveness of thyroid tumor cells." (PMID 26273300, 2015).
thyroid tumor (continued). "The aberrant methylation of tumor suppressor genes, leading to the increased aggressiveness of thyroid tumor cells, is also related to the BRAF mutation." (PMID 26273300, 2015). "Puzzlingly, however, one study demonstrated that BRAF V600E was in fact associated with increased global histone acetylation in thyroid tumor tissues and in thyroid cell lines expressing BRAF V600E." (PMID 24243688, 2014). "Using ARMS-PCR, we tested 72 thyroid tumors and determined that the frequencies of BRAF V600E mutation in the conventional, tall-cell and follicular variants of PTC were 66%, 75% and 0%, respectively." (PMID 24252159, 2013). "A T1799A transversion resulting in valine-to-glutamate substitution at codon 600 (V600E) accounts for over 80% of all BRAF mutations, and almost all mutations in thyroid tumors." (PMID 24252159, 2013). "Taking into account the high prevalence of BRAF mutations in thyroid tumours it is tempting to consider the use of BRAF inhibitors as a therapeutic approach in these cancers." (PMID 19878585, 2009). "BRAF V600E mutations were identified in 19 (39%) of the 49 thyroid tumor samples in our database." (PMID 40869231, 2025). "Of 49 thyroid tumor samples, BRAF V600E mutations were found in 19 (39%)." (PMID 40869231, 2025). "Osteopontin expression has been linked to BRAF mutations in thyroid tumors." (PMID 39410512, 2024). "Thus, BRAF non-V600E mutated tumors should be thoroughly investigated, looking for thyroid tumor progression-related molecular changes such as TERT promoter mutation." (PMID 36835466, 2023). "The BRAF encodes a serine/threonine protein kinase, which is involved in the regulation of transcriptional activity during cell growth, division and differentiation, and its mutation is associated with the development of the thyroid tumor." (PMID 36137089, 2022). "We propose to study HBME-1 and galectin-3 expression and BRAF V600E mutation in thyroid neoplasms and do a comparative analysis to determine whether there is a correlation between BRAF V600E expression and that of HBME-1 and galectin-3." (PMID 34934597, 2021). "Thus, this study aimed to assess the incidence of the BRAF V600E mutation in thyroid neoplasms at a tertiary care center and its association with various phenotypic features." (PMID 34345541, 2021). "Indeed, CCL21 was significantly associated with lymphocyte infiltration in an RNA sequencing study using clinical samples from patients with T1N0 and T2-3N1 thyroid tumors carrying wildtype BRAF and the V600E mutation." (PMID 34522174, 2021). "A BRAF V600E mutation was identified in available thyroid tumors from family members with PTC." (PMID 34326811, 2021). "The presence of TERT promoter mutations in synergy with BRAF mutations has been associated with aggressive thyroid tumor characteristics, which include lymph node metastasis, distant metastasis, tumor recurrence, multifocality, extrathyroidal extension, and patient mortality." (PMID 32751138, 2020). "TCGA database further revealed that PAX8 is negatively co-related in BRAF mutated thyroid tumors." (PMID 30760304, 2019). "In thyroid tumors, elucidation of the interaction between BRAF and Wnt signaling is just beginning to emerge, and BRAF mutations in PTC appear to cause downregulation of E-cadherin, potentially promoting Wnt signaling via a mechanism involving increased levels of cytoplasmic β-catenin." (PMID 29642644, 2018). "In a series of 96 thyroid tumours whose mutational profiles of BRAF, IDH1 and NRAS mutations and RET/PTC were previously determined, we investigated MLH1 and MGMT expression and methylation status by qPCR and methylation-specific PCR after bisulphite treatment, respectively." (PMID 23414134, 2013). "Our results indicate that sorafenib might be particularly potent in thyroid tumours harbouring BRAF mutations since, in addition to inhibition of proliferation it is also able of inducing apoptosis in these settings." (PMID 19878585, 2009).